IL1B (interleukin 1 beta)
Diseases named in the same sentence as IL1B in open-access papers (continued):
Sharing a sentence is not in itself a finding about the gene and the disease.
COVID-19 (continued). "Patients with severe COVID-19 had significantly higher Gal-3, TNF-α, IL-1β, and IL-6 than those with moderate disease." (PMID 34367188, 2021). "In the current study, we observed robust increases of proinflammatory cytokines/chemokines in sera and BALF, such as TNF-α, IL-1β, IL-6, KC, MCP-1, RANTES, and MIP-1α/β27,28 which correlate with those observed in severe COVID-19 and ARDS patients." (PMID 34952899, 2021). "Proteomics analysis revealed the up-regulation of iNOS and IL1b and IL6 proteins in lung tissue of COVID-19 patients [TE113]." (PMID 34876157, 2021). "COVID-19 patients had unique hyperinflammatory signatures across all types of peripheral blood immune cells, particularly increases in TNF- and IL-1β-driven inflammatory responses, whereas IFN responses were dominant in severe influenza patients." (PMID 33953323, 2021). "Subjects suffering from COVID-19 express a range of similar symptoms such as lymphopenia, hypercoagulability, and cytokine storm (elevation in IL-6, CRP, TNF, MCP1, IL-1β levels, and others)." (PMID 34680053, 2021). "Among these cytokines, serum levels of IL1-β, IL-6, IL-8, and TNF-α were found to be significantly increased in the critical COVID-19 patients relative to mild patients." (PMID 34276659, 2021). "The relative roles of abnormal IL-1β, NF-κB–driven, and type I/III and type II IFN responses in the immunopathology of severe COVID-19 remain controversial." (PMID 33232303, 2021). "JAK2 inhibitor Fedratinib has been proved to inhibit the production of several Th17 cytokines, including IL-6, IL-17, IL-21, IL-22, IL-1β, and TNF-α, thereby preventing Th17-related cytokine storm in COVID-19 patients." (PMID 34650550, 2021). "In the same way, IL-18 and IL-12 in combination with IL-1β induce IFN-γ secretion and promote Th cell and NK activity in both atherosclerosis and COVID-19." (PMID 34205487, 2021). "The main active ingredients of AE against COVID-19 were quercetin, kaempferol and luteolin, and the important targets were IL-6, MAPK1, MAPK8, IL-1β, and RELA." (PMID 33658066, 2021). "A recent study demonstrated that active caspase-1 (Casp1p20), IL-1β, IL-18, IL-6, and lactate dehydrogenase (LDH) were increased in the serum of patients with COVID-19, and that Casp1p20 and IL-18 are products derived from inflammasomes." (PMID 34025433, 2021). "Cytokine storm, which refers to the increased secretion of cytokines such as IL-1β, IL-6, TNF-α, and IL-18 is a characteristic of COVID-19 patients with lung damage." (PMID 34584616, 2021). "NET release can be triggered by various inflammatory mediators found elevated in severe COVID-19, including CRP, IL-1β, IL-6 and IL-8." (PMID 33684134, 2021). "Individuals in cohort one with acute COVID-19 had coagulopathy (with increased D-Dimer and fibrinogen), a marked pro-inflammatory response (elevated CRP, IL-6, TNF-α, IL-8 and IL-1β) and lymphopenia, with an increase in the neutrophil: lymphocyte ratio." (PMID 34025675, 2021). "Inflammatory cytokines IL1β, IL6, IL8, and TNFα increased in the plasma of moderate and severe COVID-19 patients." (PMID 33767630, 2021). "Compared with a severe influenza group, PBMCs from COVID-19 patients showed a high inflammatory response, and a marked TNF/IL-1β driven inflammatory response." (PMID 34746034, 2021). "Macrophage-derived cytokines like IL-1β and TNF promote adaptive TH17 responses which further contribute to inflammation seen in severe COVID-19." (PMID 34960782, 2021). "Assessment of infection-related biomarkers (CRP, ESR) and cytokine profile (IL-2R, IL-6, IL-8, IL-10, IL-1β, TNF-α, procalcitonin) on admission showed a proinflammatory state in hemodialysis patients with COVID-19." (PMID 33967613, 2021). "The IHC analysis showed increased expression of caspase-1, ICAM-1, IL-1β, IL-6, MMP-9, TNF-α, and other markers in the hearts of COVID-19 patients." (PMID 34804033, 2021).
COVID-19 (continued). "Inflammatory cytokines, such as IL-6, IL-1β, and IFN-γ that are elevated in the biospecimen of COVID-19 patients, can activate the Janus kinase (JAK)/signal transducer of activators of transcription (STAT) JAK/STAT pathway and induce the NF-kB signaling." (PMID 33917321, 2021). "In contrast, the highest contributors to dimension 1 were IL-21, IL-2, IL-1b, IL-17A, GM-CSF, IFN-γ, IL-7 and CCL3, and these cytokines were significantly decreased in acute COVID-19 patients in comparison to HC." (PMID 34572439, 2021). "The high concentration of COVA1-18 immune complexes elicited substantially less IL-1β, IL-6, and TNF than anti-spike immune complexes made from COVID-19 serum." (PMID 33979301, 2021). "The level of these cytokines was also elevated in nasopharyngeal swabs of severe COVID-19 patients compared to healthy controls (for TNF-α, IL-1β and IL-1A, for IL-6, IL-8 and IL-23)." (PMID 33995033, 2021). "A previous study that examined circulating cytokine levels from people with severe COVID-19 showed a decrease in IFN-γ and increased IL-6, CXCL8, IL-1β, and CCL2, as compared to healthy controls." (PMID 34108966, 2021). "Significantly elevated concentrations of C-reactive protein (CRP) produced as a result of macrophage stimulation by IL-1β, IL-6, or TNF-α have also been observed in COVID-19 patients." (PMID 33466589, 2021). "Levels of pro-inflammatory (IFN-γ, IL-1β, IL-6, IL-9, IL-12p70, CCL11) and anti-inflammatory (IL-4, IL-5, IL-10, IL-13) cytokines, as well as VEGF, were higher in severely ill COVID-19 patients as compared to pandemic influenza A(H1N1) subjects." (PMID 33995342, 2021). "In contrast, IL-1β, IL-4, IL-5, IL-12p70, IL-13, IL-17A, CCL11, and VEGF levels predicted severe COVID-19." (PMID 33995342, 2021). "Meanwhile, COVID-19 displayed an immune profile distinguished by increased Th1 (IL-12, IFN-γ) and Th2 (IL-4, IL-5, IL-10, IL-13) cytokine levels, along with IL-1β, IL-6, CCL11, VEGF, TWEAK, TSLP, MMP-1, and MMP-3." (PMID 33995342, 2021). "IL-1β and TNF-α, two cytokines elevated in cytokine release syndrome in COVID-19 patients, decreased KLF2 gene expression." (PMID 34253708, 2021). "In order to determine the relationship between IL-33 and proinflammatory mediators in all stages of COVID-19, we analyzed the ratio of the systemic values of IL-33 with the values of TNF-α, IL-1β, IL-6, IL-12, and IL-23." (PMID 34917631, 2021). "Conversely, higher levels of IL-1β and IFN-γ at month 1, and MIP-1β, IL-1β, MIP-1α and IFN-γ at month 3, were observed among patients with mild/moderate diseases, compared to those with severe COVID-19." (PMID 34835384, 2021). "Significantly higher levels of galectin-3, galectin-9, IL-1β, IL-1Ra, IL-10, IFN-α2, IL-6, IL-18, and TNF-α were observed in severe COVID-19 and active AOSD patients compared with HC (all p<0.001)." (PMID 34367188, 2021). "As inflammatory macrophages are suspected to be the main producer of inflammatory cytokines such as IL-6 and IL-1β, we looked for possible enrichment of inflammatory macrophages in the BAL from patients who died owing to COVID-19." (PMID 33674591, 2021). "Since NETs can induce macrophages to secrete IL1β, and IL1β enhances NET formation in various diseases, it is possible that a NET–IL1β loop is activated in severe COVID-19, and can participate in the formation of microthrombi and respiratory decompensation." (PMID 34440659, 2021). "A large number of clinical data collected from COVID-19 patients revealed high levels of circulating lactate dehydrogenase (LDH) and IL-1β in critically ill patients." (PMID 34977191, 2021). "Whereas the airway DEG profile indicated regulation by both inflammatory and inhibitory cytokines, the COVID-19 lung UPRs were markedly inflammatory, including, NFκB, IL12, TNF, IL1B, and multiple Type I IFNs." (PMID 33782412, 2021).
COVID-19 (continued). "C3a, C5a, and factor P (properdin), as well as interleukin (IL)-1β, IL-6, IL-8, tumor necrosis factor (TNF)-α, and IgM antibody levels, were higher in critical COVID-19 patients compared to mild COVID-19 patients." (PMID 34276659, 2021). "PBMCs from patients with COVID-19 exhibit active intracellular caspase-1, increased expressions of NLRP3 and ASC, and the secretion of IL-1β." (PMID 34360684, 2021). "Many studies have reported an increase in IL-6, IL-1β, and CXCL-8 in severe patients with COVID-19, which are also important factors that induce granulocyte activation and NET release." (PMID 33557911, 2021). "Higher levels of MIP-1β, IL-1β, MIP-1α and IFN-γ were observed at month 1 and 3 during mild/moderate disease, compared to severe COVID-19." (PMID 34835384, 2021). "A variety of inflammatory or anti-inflammatory cytokines, such as interleukin (IL)-1β, IL-6, IL-8, IL-10, and interferon (IFN)-γ, were elevated in severe COVID-19 patients." (PMID 34367188, 2021). "Our data showed that, compared with control subjects, COVID-19 patients have elevated levels of TNF-α and IL-1β." (PMID 34253708, 2021). "Although IL-1β, IL-6, and TNFα are well-established to influence nociceptive hypersensitivity, the possibility that additional or alternative mediators may also be driving nociceptive sensitivity in patients with COVID-19 cannot be discounted, especially in severe and critical infection." (PMID 33458558, 2021). "Being that inflammasome activity is dysregulated in COVID-19, following the infection, alveolar macrophages secrete TNF-α and IL-1β, giving rise to cell death, damage, and NLRP3 activation that trigger the acute proinflammatory cascade." (PMID 33916409, 2021). "The increase in blood concentrations of different cytokines such as interleukins and chemokines such as IL-6, IL-8, IL-10, TNF-α, IL-1β, IL-2, IP-10, MCP-1, CCL3, CCL4, and CCL5 has been described for COVID-19 patients." (PMID 34262570, 2021). "We used a multiplex cytokine assay to measure serum IL-6, IL-8, TNF, IL-1β, GM-CSF, IL-10, IL-33 and IFN-γ in 100 hospitalised patients with confirmed COVID-19 at admission to University Hospital Southampton (UK)." (PMID 32962703, 2020). "Inhibition of the E protein IC activity significantly reduced IL-1β, IL-6, and TNF-α production, corroborating its importance in COVID-19 immunopathology." (PMID 33013759, 2020). "In vitro treatment with type IFNα restored type IFNγ secretion in COVID-19 patients while the secretion of pro-inflammatory cytokines IL6 and IL1β remained stable or decreased, respectively." (PMID 33585507, 2020). "In conclusion, our findings suggest that both COVID-19 and AOSD have elevated level of ferritin and cytokines, including IL-1β, IL-6, IL-10, IL-18, and TNF-α, indicating systemic inflammation in the pathogenesis of COVID-19 and AOSD." (PMID 33552062, 2020). "Although several key proinflammatory cytokines, including IL-1β, IFN-ɣ, and TNF-α, were modestly increased in COVID-19 patients compared with healthy control participants, the increases were near the lower limit of detection of the assay." (PMID 32687484, 2020). "Under inflammatory conditions, such as COVID-19 and AOSD, ferritin is upregulated in response to IL-1β, IL-6, and IFN-γ." (PMID 33552062, 2020). "NF-κB controls the expression of many pro-inflammatory cytokines, including IL-1β, TNF-α, IL8, IL-6, all of which are induced in the cytokines storm syndrome and in COVID-19." (PMID 32708322, 2020). "The expression of several cytokines identified in the current study (i.e., IL1B, IL-6, TNF, CCL2, CXCL9, and CXCL10) were also seen in bronchoalveolar lavage (BAL) cells from COVID-19 patients, providing further support to our observation." (PMID 32882823, 2020). "A literature search was performed using the databases PubMed, EMBASE, and Web of Science to collect the levels of cytokine including IL-1β, IL-6, IL-18, TNF-α, IL-10, and ferritin in severe COVID-19 patients." (PMID 33552062, 2020).
COVID-19 (continued). "No significant changes in other cytokines or chemokines measured, including IFN-γ, IL-1β, IL-8 and TNF-α were observed in COVID-19 patients." (PMID 32943497, 2020). "Patients with COVID-19 exhibited hyper-inflammatory signatures across all types of cells among PBMCs, particularly up-regulation of the TNF/IL-1β-driven inflammatory response as compared to severe influenza." (PMID 32651212, 2020). "The activated mechanistic networks in patients with severe COVID-19 highlighted the predicted relationship between IL1A, IL1B, and TNF, and their regulation in gene datasets based on Z scores." (PMID 33138195, 2020). "During the early recovery stage of COVID-19, an increase of CD14+ monocytes with inflammatory gene expression as well as abundance of CD14++IL-1β+ monocytes were recently described." (PMID 32695683, 2020). "IL-1β and NETs form a feedback loop, which contribute to the pathogenesis of ARDS in COVID-19 patients." (PMID 33162887, 2020). "Inflammatory genes such as IL1B, TNF, and CXCL8 were also increased during aging and were further upregulated in COVID-19." (PMID 32780218, 2020). "Naringin also inhibits the expression level of cyclooxygenase (COX)-2, inducible nitric oxide synthase (iNOS), IL-1β and IL-6 via suppressing high mobility group box 1 (HMGB1) in COVID-19." (PMID 33708124, 2020). "In this regard, metal fume fever has been shown to produce fever, fatigue, muscle ache, cough, dyspnea, and an increase of several cytokines including IL-1β, IL-6, IL-8 and TNF-α, symptoms and cytokines that have already been described for COVID-19 patients." (PMID 32708755, 2020). "We measured plasma concentrations of TNF, IL-1β, IL-6, IFN-β, IFN-γ, and IL-18 in a larger cohort of COVID-19 patients." (PMID 32651212, 2020). "In COVID-19 the binding of SARS-CoV-2 to TLR, which induces IL-1β production, is potentially reversed by rapamycin." (PMID 33361522, 2020). "Significantly up-regulated levels of cytokines and chemokines including IL1-β, IL1RA, IL10, IL9, IL8, IL7, basic FGF2, GCSF, GMCSF, IFNγ, IP10, MCP1, MIP1α, MIP1β, PDGFB, TNFα, and VEGFA in blood, have been confirmed in COVID-19 patients." (PMID 33041797, 2020). "COVID-19 patients had lower levels of most classical inflammatory cytokines (G-CSF, CCL20, IL-1β, IL-2, IL-6, IL-8, IL-15, TNF-α, TGF-β), but higher plasma concentrations of CXCL10, GM-CSF and CCL5, compared to non-COVID-19 patients." (PMID 33272291, 2020). "Production of inflammatory cytokines such as interleukin (IL)-1β and tumor necrosis factor (TNF)-α by SREBP-2 or NF-κB were also increased as the severity of COVID-19 increases." (PMID 32883951, 2020). "For most severe patients with COVID-19, the levels of pro-inflammatory cytokines soared in the serum, similar to that in SARS and MERS, including IL-6, IL-1β, IL-2, IL-8, IL-17, G-CSF, GM-CSF, IP10, MCP1, MIP1α, and TNF-α." (PMID 33178109, 2020). "A retrospective cohort study including 41 COVID-19 patients observed that miR-9 levels were higher in individuals with COVID-19, particularly in non-survivors, and were strongly correlated with increased levels of IL-6, IL-1β, and TNF-α." (PMID 41595522, 2026). "A study of 1953 patients with COVID-19 showed elevated levels of IL-6, IL-8, TNF-α and IL-1B." (PMID 40236655, 2025). "We found that plasma levels of IL-1β and IL-12 in COVID-19 patients were not statistically different than in healthy controls." (PMID 40160824, 2025). "Similarly, regarding inflammatory cytokines, high levels of several cytokines, such as IL-1β, IL-2, IL-6, IL-7, IL-8, IL-10, CXCL10/IP-10, MCP-1, and TNF-α have already been described according to the severity of COVID-19." (PMID 39861879, 2025). "In our study, well-documented hallmarks of severe COVID-19, such as lymphopenia, a higher neutrophil-to-lymphocyte ratio (NEU/LYM), and the proinflammatory cytokine storm including IL-6, IL-1β, IL-8, and TNF-α were observed in adult COVID-19 patients rather than pediatric patients." (PMID 39967737, 2025).
COVID-19 (continued). "Based on the available studies, no reduced levels of IL–1Ra and IL–1β were found in patients with COVID-19." (PMID 40217938, 2025). "Based on our results, we suggest that controlling high-severity-specific markers (FOS, CXCL8, HLA-A, JAK3, ICAM1, and H2BC4) and low-severity-specific markers (IL1B, CD3D, CD4, CCL5, and SNRPB) may prevent COVID-19 progression." (PMID 41155463, 2025). "One of the key drivers of organ damage in severe COVID-19 is the cytokine storm—an exaggerated systemic inflammatory response characterized by the release of high levels of proinflammatory cytokines such as IL-6, TNF-α, and IL-1β." (PMID 40430148, 2025). "Furthermore, it should be noted that patients with MIS-C had significantly higher levels of IL-1β, IL-6, IL-12, and TNF-α compared to patients with COVID-19." (PMID 40066463, 2025). "In line with this, several lines of research suggest that post-COVID-19 may involve persistent (neuro) inflammation, indicated by increased levels of pro-inflammatory cytokines such as TNF-α, IL-1β, and IL-17A." (PMID 40686929, 2025). "In our study, we found that the interleukins primarily involved in TEN were IL-4, IL-6, and IL-12, which were modulated (downregulated) by TEN, along with augmented IL-1α, IL-1β, IL-5, IL-8, NF-κβ, and interferons (IFN; α, β, and γ), which were modulated by COVID-19." (PMID 39941142, 2025). "We observed higher levels of bilirubin, D-dimer, C-reactive protein, urea, and plasmatic cytokines, such as IL-1β, IL-6, IL-8, IL-10, IL-17A, IL-23, TNF-α, and IFN-α in individuals with the critical form of acute COVID-19 compared to individuals with the severe and/or moderate WHO clinical forms." (PMID 39861879, 2025). "Cytokine storm including inflammatory cytokines IL-1β, IL-6, IL-17, and TNF-α could be provoked in moderate and severe COVID-19 patients." (PMID 41235116, 2025). "In the present study, we quantified the expression levels of IL–1Ra, the cytokine IL–1β, the oxidative stress markers, and the baseline blood hematological parameters among patients with COVID-19 compared with a group of patients without SARS-CoV-2 infection." (PMID 40217938, 2025). "Furthermore, the long-term persistence of high plasma levels of IL–1β, IL–6, and TNF in patients with COVID-19 symptoms opens up therapeutic options based on blocking the signaling of these cytokines." (PMID 40217938, 2025). "Notably, the exacerbation in the late stages of COVID-19 has been found to correlate with specific biomarkers of CRS, including interleukin-1β (IL-1β) and tumor necrosis factor-α (TNF-α)." (PMID 41357188, 2025). "Patients with severe COVID-19 history showed significantly higher sequential organ failure assessment and acute physiology and chronic health evaluation II scores, along with elevated APTT, PCT, IL-6, IL-1β, and IL-17 levels." (PMID 41305706, 2025). "A key example is COVID-19, where NLRP3 inflammasome activation by SARS-CoV-2 results in massive release of IL-1β and IL-18, leading to cytokine release syndrome, with hyperactivation of myeloid cells and Th17 responses or IL-18-driven IFNγ production and Th1 responses." (PMID 41087719, 2025). "Smoking is linked to the exacerbation of respiratory infections, including COVID-19; it promotes inflammation by the excess production of TNF-α and transforming growth factor β (TGF-β), and diverse interleukins (IL) such as IL-1β, IL-12, IL-17, and IL-23 also have an impact on gene expression." (PMID 40142222, 2025). "scRNA-seq on immunocytes in PMBCs from patients with healthy, mild, or severe COVID-19 and severe influenza found that while severe influenza patients primarily exhibited IFN responses, COVID-19 patients showed distinctive hyperinflammatory, TNF- and IL-1β-driven responses." (PMID 40742121, 2025).